MAPT (microtubule associated protein tau)
Diseases named in the same sentence as MAPT in open-access papers (continued):
Sharing a sentence is not in itself a finding about the gene and the disease.
tauopathies (continued). "Nevertheless, MAPT mutations can cause either 3R/4R-predominant tauopathies or tauopathies with an equal expression of both isoforms." (PMID 41154499, 2025). "MAPT-bvFTD that associated with tauopathy, displayed more pronounced transcriptomic differences, since MAPT-bvFTD had shared genes with the other two forms, but with opposing directionality." (PMID 39920674, 2025). "Inclusion of pathogenic variants of human MAPT helps mimic the genetics of various human tauopathies." (PMID 40420360, 2025). "Tauopathy involves the hyperphosphorylation of microtubule-associated protein tau (MAPT), which dissociates MAPT from the microtubules and forms tau protein aggregates." (PMID 40564190, 2025). "Tauopathies are a group of neurodegenerative diseases characterized by brain deposition of neurofibrillary tangles (NFTs) of tau protein (the microtubule-associated protein tau)." (PMID 38915105, 2024). "Aggregation of the microtubule-associated protein tau (MAPT) is the hallmark pathology in a spectrum of neurodegenerative disorders collectively called tauopathies." (PMID 38994964, 2024). "Features that favour a primary neurodegenerative mechanism include the non-inflammatory tauopathy neuropathological signature and overrepresentation of microtubule-associated protein tau (MAPT) H1/H1 genotype as seen in other sporadic tauopathies." (PMID 39063198, 2024). "These kinases are directly responsible for the phosphorylation of microtubule-associated protein tau in AD, as well as other tauopathies, and contribute to pathogenic aggregation and subsequent neuronal loss." (PMID 39107885, 2024). "Protein homeostasis is perturbed in aging-related neurodegenerative diseases called tauopathies, which are pathologically characterized by aggregation of the microtubule-associated protein tau (encoded by the human MAPT gene)." (PMID 38469687, 2024). "The levels of p‐tau in CSF have been examined as a biomarker for AD and primary tauopathies including carriers with MAPT mutation, but CSF collection is invasive." (PMID 37391389, 2024). "Overall, due to the frequent observation of NFTs in DM1 brains and a clear genetic cause (DMPK mutation), DM1 can be classified a secondary tauopathy, despite the apparent missplicing of MAPT." (PMID 38554150, 2024). "hTau mice carry a full-length human MAPT transgene with H1 haplotype (which predisposes to tauopathies) in a murine tau knockout background." (PMID 38310353, 2024). "Tauopathies refers to a group of neurodegenerative disorders characterized by deposits of the microtubule associated protein Tau in neurons or/and glial cells including AD and Frontotemporal Dementia and Parkinsonism linked to chromosome 17 (FTDP‐17)." (PMID 39137949, 2024). "Epigenetic modifications, missense mutations, and rarely deletions in the MAPT gene are involved only in a fraction of tauopathies." (PMID 38554150, 2024). "Until now, nearly 60 mutations of the MAPT gene have been reported in tauopathies including FTDP-17, PSP, and CBD." (PMID 38994964, 2024). "Tauopathies are a series of neurodegenerative diseases that share the same hallmark of accumulating abnormal microtubule-associated protein tau (MAPT)." (PMID 39020075, 2024). "Mutations within the MAPT gene that encodes the tau protein form the genetic backdrop for familial forms of tauopathies, such as frontotemporal dementia (FTD), but the molecular consequences of such alterations and their pathological effects are unclear." (PMID 39145409, 2024). "Except frontotemporal dementia with Parkinsonism linked to chromosome 17 (FTDP-17), which is caused by MAPT mutations, the remaining tauopathies are associated with abnormal post-translational modifications of tau." (PMID 39232848, 2024). "P301L and P301S are also the most widely used MAPT mutations in transgenic mouse models of tauopathies, because their overexpression gives rise to robust phenotypes consisting of tau hyperphosphorylation, filament formation and neurodegeneration." (PMID 39185206, 2024).
tauopathies (continued). "One of the factors linked to the tauopathy subtype of front temporal dementia is mutations in the MAPT gene, which codes for tau protein." (PMID 38607741, 2024). "Changes in the ratio of protein isoforms produced by the genes APP and MAPT have strong associations with AD and other tauopathies." (PMID 39658200, 2024). "Tauopathies are a group of neurodegenerative diseases whose central feature is dysfunction of the microtubule-associated protein tau (MAPT)." (PMID 38255962, 2024). "Among these genes, the MAPT gene, known to encode a protein called tau, is a prominent AD hallmark and implicated in approximately 30 tauopathies, including progressive supranuclear palsy and frontotemporal lobar degeneration." (PMID 38521789, 2024). "Strang K.H., Golde T.E., Giasson B.I. MAPT mutations, tauopathy, andmechanisms of neurodegeneration." (PMID 39027123, 2024). "Genome-wide association studies have revealed that synucleinopathies and tauopathies share genetic risks such as MAPT (encoding microtubule-associated protein tau) mutations." (PMID 38528629, 2024). "Familial tauopathies exhibit distinct clinicopathological phenotypes depending on the specific microtubule-associated protein tau (MAPT) mutation." (PMID 38195580, 2024). "A neurodegenerative disease is considered a primary tauopathy when MAPT mutations/haplotypes are its primary cause and/or TAU is the main pathological feature." (PMID 38554150, 2024). "To determine the gene expression changes that are preserved in a mouse model of tauopathy, we utilized brain transcriptome data from a mouse model that overexpresses a mutant form of human tau encoding MAPT and develops tau neuropathology by 4 months of age18." (PMID 37919278, 2023). "Brains from MAPT mutation carriers most closely recapitulated the gene signatures in a dish, but we also detected an overlap among sporadic tauopathies, including AD and PSP." (PMID 36845551, 2023). "Tauopathies include a range of neurodegenerative diseases characterized by an accumulation of the microtubule-associated protein tau (MAPT)." (PMID 37033335, 2023). "Tau protein is encoded by the MAPT gene, with both exonic and intronic mutations identified in tauopathies." (PMID 36834792, 2023). "Dominantly inherited mutations in the MAPT gene, which encodes the tau protein, are sufficient to cause disease in a subset of tauopathies termed frontotemporal lobar degeneration with tau pathology (FTLD-tau)." (PMID 37730840, 2023). "We sought to determine the extent to which the 11 commonly differentially expressed genes across MAPT mutations were altered during disease course in the Tau-P301L mouse model of tauopathy." (PMID 36845551, 2023). "Most tauopathies are sporadic, while some are caused by dominantly inherited mutations in the MAPT gene." (PMID 38072056, 2023). "Tauopathies where tau abnormalities definitely cause disease are autosomal dominant MAPT mutations, which lead to hereditary forms of frontotemporal lobar degeneration." (PMID 37317972, 2023). "Surprisingly, this led to brains from GRN mutation carriers clustering closely with brains from MAPT mutation carriers, appearing to be more similar in expression profile than sporadic tauopathies." (PMID 36845551, 2023). "Accumulation of intracellular assemblies of the microtubule-associated protein tau (MAPT) underlies myriad neurodegenerative diseases termed tauopathies." (PMID 38072056, 2023). "Tauopathy is characterized by neuronal dysfunction and degeneration occurring as a result of changes to the microtubule-associated protein tau." (PMID 37013175, 2023). "Tauopathies are a group of neurodegenerative disorders characterized by the aggregation of the microtubule-associated protein tau." (PMID 37803386, 2023). "This increase is similarly observed in several transgenic mouse models of familial AD that overexpress mutant forms of APP including Tg2576, APP/PS1 and J20 mice as well as in tauopathy models carrying mutations in MAPT." (PMID 36449279, 2023).
tauopathies (continued). "This study describes a large svPPA-affected family with the MAPT P301L mutation and provides an ideal model for inferring underlying pathology and pathophysiological processes in svPPA caused by tauopathies." (PMID 36707904, 2023). "These gene signatures were largely specific for tauopathy; however, we identified a number of lysosomal genes that were altered in iPSC-neurons from MAPT mutations and in brains from GRN mutation carriers." (PMID 36845551, 2023). "In a subset of tauopathies, rare mutations in the MAPT gene, which encodes the tau protein, are sufficient to cause disease; however, the events downstream of MAPT mutations are poorly understood." (PMID 37730840, 2023). "Nevertheless, even though it was even possible to replicate the hyperphosphorylation of tau in some amyloidogenic models, it was necessary to introduce MAPT mutations associated with primary tauopathies to obtain NFTs." (PMID 37509487, 2023). "As for FTD genetic forms, MAPT mutations cause a specific tauopathy, whereas GRN mutations are generally associated with FTLD-TDP type A. C9orf72 expansion also causes FTLD-TDP, but the subtype is less regular (however, type B is the most frequent)." (PMID 37511491, 2023). "Tauopathies are a group of heterogeneous diseases characterized by intracellular deposition of abnormally folded forms of the microtubule-associated protein tau." (PMID 36922862, 2023). "These genes were selected as APOEe4 is consistently reported as a high-risk factor for AD, and MAPT is involved in tau production, which is aberrantly aggregated in AD and related tauopathies." (PMID 37358635, 2023). "This pathological folding of Tau is evident in a group of diseases collectively called tauopathies, which include AD, Pick’s disease, Huntington’s disease, and Fronto-Temporal Dementia with Parkinsonism linked to Chromosome 17 with MAPT mutations (FTDP-17T)." (PMID 37034163, 2023). "To date, more than 80 mutations in the MAPT gene, either exonic or intronic, have been discovered and are associated with different tauopathies." (PMID 37511491, 2023). "The strongest genetic risk factors for these sporadic primary tauopathies are in and around the MAPT gene, including the H1c subhaplotype, which is believed to increase MAPT mRNA expression." (PMID 37317972, 2023). "Tauopathies are neurological disorders characterized by the misfolding and aberrant aggregation of the microtubule-associated protein Tau." (PMID 37298426, 2023). "We identified a lncRNA, SNHG8, that is reduced across three types of MAPT mutations and reduced in brains from tauopathy mouse models and human patients." (PMID 37730840, 2023). "Lastly, in tauopathy mouse models (where mutations are introduced in MAPT, the tau gene), a direct relationship was established between p-tau, Aβ deposits, and RGC death, highlighting the three primary contributors to the retinal pathology associated with AD." (PMID 38137479, 2023). "Here, we coupled human iPSC models with CRISPR/Cas9 genome editing technology to create a system that allows us to distinguish the molecular signatures associated with MAPT mutations and to begin to resolve the molecular phenotypes of tauopathy." (PMID 36845551, 2023). "The coding regions of MAPT were well preserved in the cat, with the primary tauopathy rejecting a possible causal mutation related to this gene." (PMID 37760385, 2023). "Tauopathies are a group of neurodegenerative diseases characterised by microtubule-associated protein tau (MAPT) aggregation." (PMID 37037273, 2023). "In sporadic cases of tauopathies, the wild-type (WT) sequence of the microtubule-associated protein tau gene (MAPT) is linked to each disease." (PMID 36959205, 2023). "With this information at hand, we succeeded in establishing viable adult-originating hippocampal slice cultures from mice carrying the P301S MAPT mutation, causative for frontotemporal dementia, for long-term tauopathy studies." (PMID 37408256, 2023).
tauopathies (continued). "The discovery that MAPT mutations cause frontotemporal dementia with tauopathy made it even easier to overlook the tangles in Alzheimer’s." (PMID 34718566, 2022). "Tauopathies, a subset of neurodegenerative disorders that includes AD, are characterized by accumulation of fibrillar and hyperphosphorylated forms of microtubule-associated protein tau with coincident mitochondrial abnormalities and neuronal dysfunction." (PMID 35359570, 2022). "Tauopathies are a diverse group of neurodegenerative diseases defined by the aberrant aggregation and deposition of the microtubule-associated protein tau in the central nervous system." (PMID 35093145, 2022). "In preclinical stages of AD, BPND (binding potential) of 18F-AV1451 subtly elevated in MAPT mutation carriers (especially R406W) compared to controls, suggesting its use as an early prediction for MAPT mutations that lead to 3R/4R tauopathies." (PMID 35392986, 2022). "Mutations in the gene encoding tau (MAPT) can cause frontotemporal dementia, another tauopathy that is also associated with increased excitability of neuronal networks." (PMID 35732622, 2022). "Altered arginine metabolism (including the polyamine system) has recently been implicated in the pathogenesis of tauopathies, characterised by hyperphosphorylated and aggregated microtubule-associated protein tau (MAPT) accumulation in the brain." (PMID 35682712, 2022). "Even in individuals with progressive supranuclear palsy, a tauopathy in which MAPT variants are implicated, there was variability in exon 10 PSIs in different brain tissues." (PMID 35695373, 2022). "MAPT, the gene encoding microtubule-associated protein tau, is well-established known to play a critical role in tauopathies implicated in AD." (PMID 35729600, 2022). "Neurofibrillary tangles (NFT), inclusions composed of toxic hyperphosphorylated forms of the microtubule-associated protein tau (p-tau), are the defining neuropathological feature of a category of neurodegenerative diseases termed tauopathies." (PMID 36316708, 2022). "Some familial tauopathies are consequent to MAPT mutations resulting in excess exon 10 inclusion by splicing dysregulation and thus elevation of 4R isoforms." (PMID 36361774, 2022). "Abnormal tau is implicated in CIN by both the effects of tau hyper- phosphorylation (as seen in tauopathies) and by mutations of the MAPT gene affecting increased instability and vulnerability of chromatin." (PMID 35784845, 2022). "The microtubule-associated protein tau (MAPT) is a causative gene in tauopathy diseases such as FTD, and progressive supranuclear palsy (PSP)." (PMID 35812232, 2022). "The tauopathies are characterized by the abnormal accumulation of the microtubule-associated protein tau, encoded by the MAPT gene." (PMID 35067193, 2022). "Transgenic mouse models (mutations in the MAPT gene) recapitulate pathological features of tauopathy and have greatly advanced our understanding of disease mechanisms." (PMID 35128565, 2022). "Familial tauopathy is associated with abnormal phosphorylated tau protein, and studies showed that mutations in the MAPT gene are sufficient enough to induce the formation of pathological tau protein." (PMID 36361631, 2022). "PSP belongs to a group of neurodegenerative diseases characterized by the accumulation of abnormal forms of the microtubule-associated protein tau, commonly referred to as the tauopathies, in different cells and regions of the brain." (PMID 35815712, 2022). "Several types of tracers have been applied to map the pattern of tau accumulation in familial FTLD, especially in individuals with MAPT mutations thought to be tauopathy." (PMID 36051222, 2022). "In particular, aberrant splicing of MAPT, encoding microtubule-associated protein tau, potentially causes tauopathy." (PMID 35216455, 2022). "Tauopathy due to MAPT mutations can present various types of pathology, depending on the particular mutations." (PMID 34402107, 2022).
tauopathies (continued). "The most significantly altered protein was MAPT, microtubule-associated protein tau, a key protein involved in neurodegenerative diseases such as AD and tauopathies." (PMID 35892672, 2022). "Further work to replicate the findings in other MAPT mutation cohorts (and other primary tauopathies) as well as longitudinal analysis within the GENFI cohort will be important." (PMID 36045450, 2022). "MAPT mutations have different types of underlying tauopathies, leading to different tracer binding patterns." (PMID 36051222, 2022). "MAPT mutations cause tauopathies that present in about 45% of cases with a bvFTD syndrome followed by unspecified dementia (34.6%), parkinsonian syndrome (4.9%), RS (4.2%), amnestic syndrome (3%), CBS (1.8%), nfaPPA (1.8%), and svPPA (1.8%) phenotypes." (PMID 35911892, 2022). "We now know that mutations along the MAPT gene, which codes for tau protein, can cause various disorders called tauopathies." (PMID 36062211, 2022). "Given that APP-models were able to generate hyperphosphorylated tau (ptau), but not intraneuronal neurofibrillary tangles (NFTs), the incorporation of mutated MAPT gene allowed for investigating the tauopathy component of AD." (PMID 35628216, 2022). "Tauopathies and synucleinopathies are characterized by abnormal aggregation of microtubule-associated protein tau (Tau) and alpha-synuclein (aSyn), respectively." (PMID 35655068, 2022). "Mapt, microtubule-associated protein tau, is a common pathological hallmark of tauopathy spectrum disorders, including AD, frontotemporal lobar degeneration, and Parkinson’s disease." (PMID 35892672, 2022). "Accordingly, the MAPT H1 haplotype that is known to be associated with tauopathies decreases exon 3 inclusion." (PMID 35203451, 2022). "For instance, tauopathies arise due to hyperphosphorylation and the misfolding of microtubule-associated protein Tau (MAPT) isoforms, which leads to its pathological accumulation in neurons or glial cells." (PMID 35741796, 2022). "PS19 mice bearing the MAPT P301S mutation show an early and rapidly progressing neurodegenerative phenotype of tauopathy, and hence are a valuable transgenic mouse model to better understand the onset and development of tauopathies." (PMID 35682712, 2022). "Mutations in the MAPT gene inherited as an autosomal dominant trait are strongly associated with tauopathies." (PMID 33467748, 2021). "Corticobasal degeneration (CBD) is a sporadic 4R tauopathy with only a few MAPT mutations reported in rare familial cases (e.g., p.G389R and p.N410H)." (PMID 34425874, 2021). "AD is characterized by amyloid plaques made up of β-amyloid peptide and neurofibrillary tangles, comprising of hyperphosphorylated Microtubule Associated Protein Tau (MAPT or Tau), leading to loss of neurons and synapses as seen in other tauopathies." (PMID 33407732, 2021). "Systemic LPS administration to tauopathy mice evidently enhances microtubule-associated protein tau (MAPT) phosphorylation at theSer202 and Thr231 sites, suggesting that enhanced microglial activation is critical in exacerbating MAPT phosphorylation." (PMID 34899188, 2021). "All tauopathies share ectopic expression, mislocalization, or aggregation of the microtubule associated protein TAU, encoded by the MAPT gene." (PMID 34831288, 2021). "Neurodegenerative diseases classified as tauopathies have in common intraneuronal accumulation of different isoforms of the microtubules associated protein tau (MAPT) characteristic of each disease." (PMID 33415685, 2021). "A major class of neurodegenerative diseases are tauopathies which are characterized by intra-cellular inclusions of the microtubule-associated protein tau (MAPT) in neurons." (PMID 34532319, 2021). "Microtubule-associated protein tau is abnormally aggregated in neuronal and glial cells in a range of neurodegenerative diseases that are collectively referred to as tauopathies." (PMID 34425874, 2021).